HIF1A (hypoxia inducible factor 1 subunit alpha)
Diseases named in the same sentence as HIF1A in open-access papers (continued):
Sharing a sentence is not in itself a finding about the gene and the disease.
cancer (continued). "HIF-1α plays a key role in the induction of glycolysis, as the oncogenic modulations leading to HIF-1α stabilization can promote alterations in cancer cell metabolism." (PMID 30736384, 2019). "HNK decreases the expression level of HIF-1α and suppresses the hypoxia induced cancer-promoting pathway." (PMID 31618928, 2019). "Since, a previous study demonstrated that HIF-1α is the master regulator during hypoxia response, which leads to cancer cells’ chemoresistance via provoking multiple adaptive responses." (PMID 28442599, 2019). "This recruitment is related to cancer cell k-ras expression, hydrogen peroxide excretion, loss of caveolin-1 and induction of CAF oxidative stress, HIF-1α, NF-κB and autophagy." (PMID 31198853, 2019). "In contrast, the hypoxia‐inducible factor HIF‐1α, which has been revealed as a master regulator of the stemness properties of cancer stem cells, is increased in HepG2SF1 and Huh7 cells compared with their parental cells and decreased in AMPK‐transfected cells." (PMID 30959553, 2019). "Knockdown of PDK-1 reverts the Warburg phenotype, diminishes the normoxic HIF-1α expression, hypoxic cell survival, invasion, and inhibits cancer development." (PMID 31803621, 2019). "Our results showing an effect of lactate on expressions of MYC and HIF1A genes are consistent results of others showing an upregulation of the glycolytic pathway in cancer." (PMID 32010625, 2019). "Accordingly, HIF-1α, involved in cell cycle deregulation, apoptosis, angiogenesis induction and proliferation in cancer, constitutes a predictive marker of resistance to radiotherapy (RT)." (PMID 31739546, 2019). "Activation of P70-S6K1 leads to increased activity of ribosomal protein S6 (RPS6), which induces translation of HIF-1α mRNA into protein, thus serving as the major determinant of the rate of HIF-1α protein synthesis in many cancers." (PMID 31083403, 2019). "Due to the complex functional mechanism and regulatory roles of HIF-1a in hypoxic stress, the possible role of HIF-1a gene SNPs in cancer susceptibility has evoked intensive investigation." (PMID 31762805, 2019). "The increase in lactate production and the activation of HIF-1α by the upregulated canonical WNT signaling are associated with the increase of angiogenesis and poor prognosis of cancers." (PMID 31803621, 2019). "In the microenvironment of solid tumors, HIF-1α plays a key role in activating both aerobic and anaerobic glycolysis, and increasing metabolic flux of glucose, lipid, and glutamine in cancer cells." (PMID 31683709, 2019). "This is thought to occur through a mechanism mediated by increased expression of organic anion transporter peptides (OATPs) and hypoxia-inducible factor 1-alpha (HIF1α), both of which are upregulated in cancer cells." (PMID 31653966, 2019). "Among these transporters, GLUT1 and GLUT3, which are induced by hypoxia-inducible factor 1α (HIF-1α), have been shown to increase glycolysis and cancer progression." (PMID 31027222, 2019). "Mechanistically, we revealed that matrine significantly decreased the messenger RNA (mRNA) and protein expression of HIF-1α, a critical transcription factor in reprogramming cancer metabolism toward the Warburg effect." (PMID 31849679, 2019). "Both VEGF and HIF1A allow cancer cells coping with oxidative stress and unbalanced redox status arising from the rapid growth and scarcity of oxygen and nutrients of advanced tumors." (PMID 31540249, 2019). "Hypoxia Inducible Factor 1 Alpha Subunit (HIF1α) is an important mediator of the cellular response to hypoxia and is involved in the cellular regulations of cancer cells, including angiogenesis, erythropoiesis, invasion, and metastasis." (PMID 31217907, 2019).
cancer (continued). "This revealed a pilot proof of HIF-1α mRNA and protein expression modulation in response to EZN-2968 thereby indicating inhibition of HIF-1α mRNA has potential as a target for cancer therapy." (PMID 31485300, 2019). "S1P released by dying cancer cells also triggered HIF-1α accumulation in macrophages downstream of S1PR1, even under normoxic conditions." (PMID 31379883, 2019). "Tumor microenvironment tend to be hypoxic in nature and HIF-1α helps the cancer cells to adapt to the low oxygen environment." (PMID 31618928, 2019). "Under normal conditions, reactive oxygen species (ROS) accumulation leads to apoptosis in both normal and cancer cells, whereas the HIF-1α signaling pathway decreases the production of ROS and preserves SC properties leading to drug resistance in CSCs." (PMID 31505803, 2019). "As for several other cancer types, HIF-1α promote the resistance to drug-induced apoptosis chemoresistance of HCC cells." (PMID 31060333, 2019). "The role of increased activity of hypoxia-inducible factor-1 (HIF-1), especially HIF-1α is well known in cancer progression." (PMID 31551770, 2019). "The stimulation of cancer cell stemness by HIFs is well documented, with studies revealing HIF-1α and HIF-2α to be central to CSC stemness." (PMID 30761299, 2019). "Pathological processes, like cancer-related hypoxia, permit cell survival via activation of hypoxia transcriptional programs, comprising HIF-1α (hypoxia-inducible factor 1α), NFĸB, PI3K, and MAPK pathways." (PMID 31652660, 2019). "Under hypoxic conditions, upregulated HIF-1α directly binds to a hypoxia-responsive element on the proximal miR-210 promoter and induces miR-210 expression in cancer cells." (PMID 31816897, 2019). "Of note, as for many cancers, there is a relationship between HIF-1α activity and resistance to drug-induced apoptosis of HCC cells." (PMID 31881713, 2019). "Cancer cells are characterized by a metabolic shift in cellular energy production, orchestrated by the transcription factor HIF-1α, from mitochondrial oxidative phosphorylation to increased glycolysis, regardless of oxygen availability (Warburg effect)." (PMID 30762162, 2019). "Although, targeting HIF1α directly or indirectly appears to be promising for future cancer therapy; the results of further clinical studies targeting HIF1α must be first made available." (PMID 31554283, 2019). "Hypoxia, a prominent characteristic of the microenvironment of cancers, can exert specific effects on cell cycle control, and DNA replication through HIF1α-dependent pathways." (PMID 31479497, 2019). "Some papers report that the overexpression of HIF-1α is significantly related to the increased [18F]FMISO uptake on the various kinds of malignant tumors." (PMID 31073705, 2019). "According to an earlier survey of cancer cell lines, there was about a 50% incidence of HIF-1α stabilizing under normoxic conditions in cancers." (PMID 30761299, 2019). "Increased HIF-1α expression has been observed in a broad range of human cancers and often correlates with poor prognosis." (PMID 30177838, 2019). "Several of the genes, including MMP1, MMP2, TIMP1 and HIF1A, are known cancer genes and facilitate stromal invasion." (PMID 31748560, 2019). "Hypoxia is another important activator of MDSCs; it increases the expression of HIF-1α in cancer cells." (PMID 31048856, 2019). "Upon facing hypoxia, cancer cells switch their metabolism to glycolytic pathways through HIF-1α signaling." (PMID 31078780, 2019). "They found that HIF‐1α expression was increased in most patients, with weakly positive expression in most cancer tissues and strongly positive expression in the adjacent tissues." (PMID 31411003, 2019). "Highly-glycolytic cancer cells express HIF-1α, which under normal conditions, is ubiquitinated and degraded in the cytoplasm." (PMID 31450598, 2019).
cancer (continued). "Accumulated HIF-1α binds to hypoxia-responsive elements (HREs) on the promoter of its target genes, which are involved in aggressive behaviors of cancers, including blood vessel formation, metabolic reprogramming and metastasis/invasion." (PMID 31078780, 2019). "After the expression of HIF-1α mRNA was silenced, cancer cells are in a state of low oxygen and metabolism, as so to the death of cancer." (PMID 30911540, 2019). "This is in line with most previous studies indicating that HIF-1α promotes survival in cancer and endothelial cells." (PMID 30804946, 2019). "The inhibition of HIF‐1α leads to the depletion of downstream proteins, which makes the cancer cell more amenable to the lethal hypoxic environment." (PMID 29893459, 2019). "Lactate has the ability to induce angiogenesis as well as cell migration, since lactate produced by cancer cells induces the expression of VEGFA in a HIF-1α-dependent manner." (PMID 31083487, 2019). "In order to survive the hypoxic microenvironment, cancer cells activate several biochemical pathways via the HIF-1α." (PMID 31485300, 2019). "We know from the literature that activated HIF-1α is able to stimulate the expression of several growth factors and glycolytic enzymes in human cancer cells." (PMID 31903166, 2019). "Based on these findings, HIF‐1α/VEGF signal pathway is considered to be an important target for the treatment of angiogenesis‐related diseases including metastasis of cancer." (PMID 30653763, 2019). "Given the critical roles of HIF1α in modulating the growth of cancer cells, interfering the expression of HIF1α is an attractive strategy to inhibit the malignancy of cancers." (PMID 30988076, 2019). "Since HIF-1α plays multiple roles in infections, inflammation, and cancer cell stemness, our findings suggest a potential clinical value of chloramphenicol in the treatment of these conditions." (PMID 30609861, 2019). "To further confirm the relationship between YAP and HIF-1α, we first examined the localization of YAP and HIF-1α in CD133− cancer cells following rhHMGB1 treatment by immunofluorescence." (PMID 31558702, 2019). "During the development of PM, hypoxia inducible factor-1α (HIF-1α) plays a key role in activating both aerobic and anaerobic glycolysis, increasing the uptake of glucose, lipid, and glutamine into cancer cells." (PMID 31683709, 2019). "KEGG pathway analysis shows that “HIF1A direct-targets” are enriched in metabolic and cancer pathways similar to pathways affected by HIF1A silencing “exclusively in hypoxia” (FDR ≤ 0.05)." (PMID 30808328, 2019). "Under hypoxic conditions, HIF-1α enhances the expression of PD-1 ligand (PD-L1) on the surface of cancer cells by directly binding to the HRE in the PD-L1 promoter." (PMID 31817259, 2019). "Vanillic acid significantly inhibits HIF-1α expression induced by hypoxia in various human cancer cell lines." (PMID 30678221, 2019). "HIF1-α in cancer cells promotes glucose uptake by upregulation of GLUT1, GLUT3, and increased expression of glycolytic enzymes further promoting glycolysis and acidosis." (PMID 31636636, 2019). "In our study, the pathway analysis showed that besides expected HIF-1α pathways, important cancer progression, angiogenesis, and metastasis-related pathways were changed in MCCL." (PMID 31594284, 2019). "Major oncogenes, such as c-Myc, and HIF-1α, are reported to be master inducers of cancer glycolysis through direct or indirect transactivation of cancer glycolytic genes." (PMID 31261749, 2019). "The transcription factor HIF1α is regulated by ERα and that increased HIF1α expression confers endocrine resistance to ERα+ cancer cells." (PMID 31178825, 2019).
cancer (continued). "For example, SIRT3 can restrain the “Warburg effect” by controlling HIF-1α and change the cancer cell metabolism programming from highly glycolytic toward oxidative phosphorylation." (PMID 31687086, 2019). "Hypoxia-inducible factor 1α (HIF-1α), a subunit of hypoxia-responsive HIF-1 transcription factor (TF), is implicated in the pathogenesis of cancer initiation and progression." (PMID 31076568, 2019). "In fact, lactic acid activates VEGF, which promotes angiogenesis in tumors, triggers the exponential growth of cancer cells, and activates HIF-1α." (PMID 31261749, 2019). "DON was previously reported to modulate HIF-1α expression in the process of oxidative stress in chickens and constitutively modulates the expression of NFΚB in the inhibition of cancer cell growth." (PMID 31083547, 2019). "Consistent with this, HIF-1α and HIF-2α deficiency have revealed isoform-specific effects on cancer cells, indicating that they can act in different ways to promote malignancy and cancer progression." (PMID 31151160, 2019). "Here we use genetic ablation of this enzyme to induce indolence in two cancer types, and show this is reversed by allowing the stabilization of Hypoxia Inducible Factor-1 alpha (HIF-1α)." (PMID 30796225, 2019). "The roles of numerous small molecules used to treat various cancers by inhibiting HIF-1α activity have been characterized." (PMID 30755586, 2019). "Caloric restriction specifically influences the IGF-1/PI3K/Akt/HIF-1α signaling pathway, which regulates several cancer hallmarks like evasion of apoptosis, cell proliferation, and angiogenesis." (PMID 31687086, 2019). "MSC-derived exosomes shuttled miR-16 and miR-100 (inhibiting the mTOR/HIF-1α/VEGF pathway) to the nearby cancer cells and decreased their VEGF expression, subsequently resulting in inhibition of the endothelial cells’ vascular behavior." (PMID 31395836, 2019). "Of note, it has been reported that elevated O-GlcNAcylation in cancer cells stabilizes HIF-1α in an indirect manner, thereby reinforcing the Warburg effect in what appears to be negative feedback loop toward homeostatic O-GlcNAcylation levels." (PMID 31157165, 2019). "BNIP3, a BCL-2 family protein, is known to be transcriptionally regulated by HIF-1α and to be involved in cancer cell death in hypoxic conditions." (PMID 31078780, 2019). "In hypoxic Hep3B, cervix HeLa, colon HCT116, and lung A594 cancer cells, HIF-1α also induces decreased COX4-1 protein contents." (PMID 31600993, 2019). "PVT1 upregulates the expression of HIF-1α by binding to miR-199-5p and miR-186, thus further facilitating the proliferation of cancer cells." (PMID 31497532, 2019). "Given the contribution of Hif-1α and hypoxia to malignant and radiotherapy-resistant phenotypes in cancer, researchers have been trying to eliminate Hif-1α-active cells using strategies that hijack E3 ubiquitin ligases." (PMID 31632280, 2019). "The Spearman analysis also revealed a positive linear association among HIF-1α, MDR1 and LAPTM4B in all the studied cancer patients." (PMID 30746305, 2019). "GLUT-1 is a potential intrinsic marker of hypoxia in cancer, and HIF-1α regulates the expression of several hypoxia-response genes, including GLUT-1." (PMID 31105886, 2019). "In the cancer cell study, cellular metabolism was targeted by inhibiting translation of the HIF-1α transcription factor using an AUR concentration of 100 μM." (PMID 31336718, 2019). "HIF1-α induction has also been associated with IL-23 production in dendritic cells; this link between HIF1-α and PKM2 has been previously established in cancer cells." (PMID 31139181, 2019). "Hypoxia, acting through HIF-1α, results in a low production of ROSs and high antioxidant defense in cancers such as leukemia." (PMID 31816897, 2019).
cancer (continued). "At the same time, to provide full justification for the use of CI inhibitors such as metformin in clinical practice, the dissection of the mechanisms linking CI inhibition to cancer growth arrest is warranted, especially those behind HIF-1α destabilization." (PMID 30796225, 2019). "Hypoxia is the most common characteristic of solid tumors and drives cancer metastasis by increasing the expression of HIF-1α." (PMID 31624493, 2019). "HIF-1α functions as a master regulator in the reprogramming of cancer metabolism in favor of aerobic glycolysis." (PMID 31737114, 2019). "Focusing on the role of lncRNAs in cancer development, hypoxia induced downregulated lncRNA-LET induces hypoxia associated cancer cell metastasis through affecting HIF-1α expression and stability by interfering with mRNA." (PMID 30971290, 2019). "The positive correlation among all the studied cancers suggest similar upregulation of LAPTM4B leading to increased HIF-1α and MDR1 genes." (PMID 30746305, 2019). "The involvement of these main JmjC-KDMs highlight the importance of HIF-1α-dependent epigenetic regulation in hypoxia, leading to several molecular changes, like cell cycle arrest and DNA repair, which contribute to cancer progression." (PMID 31739546, 2019). "Some cancers have also shown competition between the repressive HIF-1α and activating c-Myc transcription factors binding to the E-box of the ASS1 promoter." (PMID 35582579, 2019). "It is important to note that HIF1α activity varies between different cancer cell lines under the same level of hypoxia." (PMID 31330834, 2019). "MCT4 is regulated by HIF-1α and NF-κB and is highly expressed in CAFs, allowing shuttling of lactate between CAFs and cancer cells." (PMID 31198853, 2019). "P4 mixture significantly down-regulated the expression of VEGF and HIF1A on both Caco2 and HepG2 cancer cells." (PMID 31540249, 2019). "Taken together, our data demonstrate that HIFs are essential to promote survival of cancer cells regulating cell death pathways and that drug treatment alone of cancer cells expressing both HIF-1α and HIF-2α quickly induce resistance to apoptotic cell death." (PMID 31151160, 2019). "HIF-1α can also intervene in the expression of enzymes that polymerize and regulate the alignment of collagen fibers and activity of integrins to promote cancer migration." (PMID 31711497, 2019). "The increased intracellular T3 concentration directly contributes to cancer progression, by inducing the expression of HIF1α, which in turn activates the expression of proangiogenic VEGF." (PMID 30814976, 2019). "Taken together, these data documented that ALM induced HIF-1α dependent cell apoptosis to suppress cancer cell growth." (PMID 31083403, 2019). "Omental milky spots provide an hypoxic niche mediated by HIF-1α for the implantation, nutrition and proliferation of detached cancer stem cells." (PMID 31198853, 2019). "Our results showed that the expression levels of HIF-1α in BxPC-3 cancer cells increased in a dose-dependent manner in response to high glucose concentrations compared with normal physiological glucose levels (5.5 mM glucose)." (PMID 30455857, 2018). "It is known that HIF-1α increases blood, oxygen, and energy supply to tumors, attenuating hypoxia, and has crucial functions in cancer cell metabolism, angiogenesis, and metastasis." (PMID 29770329, 2018). "Hypoxia-induced epithelial–mesenchymal transition (EMT), driven by hypoxia-inducible factor 1α (HIF-1α), is involved in cancer progression and metastasis." (PMID 29568752, 2018). "Hypoxia-activated HIF-1α induces cancer EMT through diverse molecules and pathways, including inflammatory cytokines, epigenetic regulators, and transcription factors/repressors." (PMID 29996493, 2018). "Mechanistically, B7H3-induced metabolic shift in cancer cells is mediated by HIF1α, a master regulator in the reprogramming of cancer metabolism in favor of glycolysis, revealing a new mechanism for the Warburg effect in cancer cells." (PMID 30035102, 2018).